SMAD2 (SMAD family member 2)
Diseases named in the same sentence as SMAD2 in open-access papers (continued):
Sharing a sentence is not in itself a finding about the gene and the disease.
tumor (continued). "In a cohort of PDAC patients, SMAD4/DPC4-negative tumours with high levels of phospho-SMAD2 were more aggressive and had a poorer prognosis." (PMID 37685308, 2023). "SMAD4 has tumor suppressor activity, and, in its absence, the SMAD2/SMAD3 heterodimer mediates the oncogenic effects of TGFB by activating a SMAD4-independent signaling pathway." (PMID 37509254, 2023). "In fact, SMAD2 exhibits overexpression in many types of human cancers, including GC, and functions as an oncogene by stimulating cell proliferation and tumor metastasis." (PMID 37415735, 2023). "And patients with high phosphorylated SMAD2 levels in immune cells or tumor cells had numerically higher ORR." (PMID 36817443, 2023). "In CRC, this phenomenon was mainly manifested by mutations in TGFBR2, SMAD2, and SMAD4, which suppressed the tumor inhibitory ability of TFG-β." (PMID 36782251, 2023). "Upregulation of a pseudo-EMT signature and of known Smad2,3 target genes such as Pmepa1 and Skil within the tumor cells is consistent with increased autocrine Activin-A signaling." (PMID 38304252, 2023). "By knocking down SMAD3 in ADC-TAFs similarly increased TGF-β1/SMAD2 activation and reduced their fibrotic phenotype and anti-tumour response to nintedanib." (PMID 37685308, 2023). "Immunostaining with the estrogen receptor α antibody (ERα, green) showed that the stroma and epithelium of both control and Smad2/3 cKO mice expressed ERα, suggesting that the tumor’s estrogen response was occurring via the transcriptional activity of ERα." (PMID 36906706, 2023). "Given the essential role of Smad2/3 signaling in TRIM9-induced tumor progression, it should be feasible to suppress Smad2/3 molecule to improve the outcome of chemotherapy in TRIM9-high patients." (PMID 37249822, 2023). "We observed significantly high protein expression of p-Smad2 under high flow rate conditions compared to low flow rate conditions, indicating the tumor suppressor effect of TGF-β1 under high flow conditions." (PMID 36863017, 2023). "High-risk tumor depths (≥4 mm) demonstrated a markedly significant negative dependence on both phosphorylated SMAD2 (C.C −0.214; p = 0.001) and SMAD3 (C.C −0.200; p = 0.002), which is consistent with a tumor-suppressive role for SMAD2/3 activators in cSCC." (PMID 36980718, 2023). "And Smad2/3 linker phosphorylation is an essential marker of cancer stem cells and correlates with chemoresistance development in several tumor types." (PMID 37249822, 2023). "Canonical TGF-β signaling promotes Smad2/3 phosphorylation and transformation from epithelial phenotype to mesenchymal phenotype, which enhances the invasive capacity of tumor cells." (PMID 37573354, 2023). "PSPC1 is an interaction partner of Smad2/3 as TGF-β1 the contextual determinants of the response will be dichotomous TGF-β1 function changes from tumor inhibition in precancerous cells to metastasis promotion in malignant cells." (PMID 36894530, 2023). "TGF-β1 contained in pancreatic cancer-derived EVs suppresses NK cell cytotoxic activity against tumor cells via SMAD2/3-dependent signal pathway, resulting in immune tolerance and tumor immunosuppression." (PMID 37064113, 2023). "To determine the effect of E2 on tumor development, we ovariectomized 8-week-old control and Smad2/3 cKO mice and implanted a placebo or 90-day-release E2 pellet." (PMID 36906706, 2023). "In nude mice xenograft model, AMTB treatment augmented tumor cells’ sensitivity to cisplatin, by smodering Smad2 and Smad3 phosphorylation and, therefore, repressing the activation of TGFβ signaling, which was implicated in tumorigenesis and tumor progression." (PMID 36844925, 2022).
tumor (continued). "HER2 heterogeneity was detected in the primary tumor, and p-Smad2 and c-Met were expressed in both HER2-negative and HER2-positive areas." (PMID 35650563, 2022). "For instance, Foxp1 interacted with Smad2/3 and suppressed the tumor-reactive T cells’ response to TGF-β in advanced tumors." (PMID 36119068, 2022). "Along this line, we observed that SMAD2/3 depletion reduced the spreading of engrafted tumor cells over chicken chorioallantoic membranes (CAMs)." (PMID 36207615, 2022). "Consistently, SOX9 and SMAD2 were significantly elevated in tumor cells from the diversity-high group." (PMID 35322024, 2022). "The expression of TGF‐β, p‐SMAD2, and three tumor proliferation markers (p‐PI3K, p‐p38, and p‐ERK1/2) exhibited a similar trend as that of Arg1." (PMID 35128843, 2022). "Kaempferol and TGF-β receptor (ALK5) binding inhibits the phosphorylation and translocation of Smad2 and reduces the expression of Smad4, thus inhibiting the proliferation, migration, and invasion of tumor cells." (PMID 36147444, 2022). "The RGS5-TGFβ-Smad2/3 axis converts pro-to anti-apoptotic signaling in tumor-residing pericytes and assists tumor growth." (PMID 36561319, 2022). "Instead, tumors displayed inconsistent patterns of changes, with decreased expression of tumor cell p-SMAD2, p-SMAD3, and p21 in 4 (29%), 7 (50%), and 5 (37%) samples, respectively, and an increase in tumor cell Ki67 expression in 5 (37%) samples." (PMID 35727629, 2022). "Our findings support a model in which KIT stimulates TGFβ expression to promote stroma formation and activation—resulting in CRC progression —while simultaneously protecting the tumor cells against TGFβ-induced growth inhibition through suppression of SMAD2." (PMID 35842424, 2022). "Although we showed that SMAD2 depleted cells generated larger tumor xenografts, a previous study has shown that selective knockdown of SMAD2 inhibited cell growth in vitro." (PMID 35681731, 2022). "Some TFs are associated with multiple PTPs, such as several tumor metastasis regulators (ZEB1, SNAI3, and SMAD2)." (PMID 36341348, 2022). "Then, as a crucial tumor suppression factor of PCa epithelium, protein SMAD2 is inhibited, resulting in TF ESF1 upregulation and oxidatively induced DNA damage." (PMID 35164166, 2022). "More precisely, we demonstrated that the tumor suppressive function of SMAD2 remained intact while the pro-invasive role of SMAD3 was exacerbated under hypoxic conditions." (PMID 35681731, 2022). "TGF-β secreted by tumor cells binds to and activates receptors on the precursors of CAFs, resulting in the phosphorylation of Smad2 and Smad3." (PMID 36109762, 2022). "Smad2/3 mediate TGFβ signaling and are thus involved in regulation of tumor progression and metastasis by epithelial to mesenchymal transition." (PMID 35899209, 2022). "Immunostaining revealed that Tgfβr2 and p-Smad2 were highly expressed in p18−/−; Brca1MGKO tumor cells, and that the expression pattern of Tgfβr2 in p18−/−; Brca1MGKO tumors was similar with the pattern in p18−/−; Brca1+/− tumors." (PMID 35236825, 2022). "The tumor suppressor function of SMAD2 and the pro-tumorigenic role of SMAD3 have already been demonstrated in various models, but only a few studies have been conducted to assess the selective importance of SMAD2 vs. SMAD3 in cancer progression." (PMID 35681731, 2022). "SMAD2/3 are ubiquitously expressed, but studies have shown that their expression can be modulated by different stimuli present in the tumor microenvironment." (PMID 35681731, 2022). "In this mechanism, FOXP3 likely exerts its inhibitory effects on tumor metastasis by regulating the TGF-β/Smad2/3 pathway." (PMID 36235242, 2022).
tumor (continued). "Both Tgfβr2 mRNA and protein levels, as well as the level of phosphorylated-Smad2 (p-Smad2), were significantly increased in p18−/−; Brca1MGKO tumors relative to those in tumor-free mammary tissues of the same mice." (PMID 35236825, 2022). "In nonmalignant epithelial cells with intact TGF-β pathway signaling, TGF-β is antiproliferative, and neutralization is expected to result in decreased tumor cell phosphorylated SMAD2 (p-SMAD2), p-SMAD3, and p21 and increased Ki67 (a marker of proliferation)." (PMID 35727629, 2022). "Downstream of the TGF-β pathway, SMAD3 and CTNNB1 form a complex with other molecules in the nucleus and induce EMT, proliferation, and angiogenesis in desmoid tumor cells via the SMAD2/3 pathway." (PMID 36497457, 2022). "In conclusion, our study identifies high KIT expression as a third potential mechanism that is utilized by tumor cells to evade growth suppression by TGFβ, presumably by downregulating one of the core signaling components in the pathway, SMAD2." (PMID 35842424, 2022). "Taken together, these findings suggest that cancer progression is related to increased pro-tumorigenic SMAD3 signaling, which prevails over SMAD2 signaling in the hypoxic tumor microenvironment." (PMID 35681731, 2022). "When the positive cells were quantified, we found that H scores for both Tgfβr2 and p-Smad2 in p18−/−; Brca1MGKO tumor cells were significantly more than the H scores in p18−/− counterparts." (PMID 35236825, 2022). "Overall, these findings further emphasize the SMAD2/3 dichotomy in tumor progression and suggest that SMAD3 expression is important for cancer cell invasion in response to hypoxia." (PMID 35681731, 2022). "We propose that KIT induces a pro-fibrotic tumor microenvironment by stimulating TGFβ expression, and protects the tumor cells from tumor-suppressive TGFβ signaling by inhibiting SMAD2 expression." (PMID 35842424, 2022). "Phosphorylated SMAD2/3 forms a complex that transfers into the nucleus, binds with DNA and regulates the transcription of target genes, thereby promoting tumor cell invasion, migration, and EMT." (PMID 34671554, 2021). "Apart from tumor promoting role of SMAD2 and SMAD3, emerging evidence revealed that TGFβ/SMAD signaling played central role in the induction of apoptosis." (PMID 33511320, 2021). "Consistent with this, transcription factors Smad2/3 were less frequently phosphorylated in CD8+ T lymphocytes from B16F10E-KO than B16F10E tumours." (PMID 34471106, 2021). "Results indicated that p-SMAD2 was significantly enhanced in patient tumor tissues compared to normal tissues, indicating probable activation of the canonical TGFβ pathway." (PMID 34379688, 2021). "Collectively, these results demonstrated that ISL inhibited the tumor metastasis via up-regulating the E-cadherin and down-regulating the N-cadherin, p-Smad2/3, and TWIST1/2 protein expression in the xenograft animal model." (PMID 33799801, 2021). "Possible activation of the canonical TGFβ pathway by phosphorylation of SMAD2 in tumor tissues suggests its role as an intracellular tumor promoter." (PMID 34379688, 2021). "We demonstrate that lack of PTEN triggers a PI3K/AKT-dependent nuclear localization of SMAD2/3, which acts as a tumor suppressor that restrains proliferation endometrial cells lacking PTEN." (PMID 34638474, 2021). "Mice harboring bigenic tumors contained a greater number of circulating tumor cells and lung metastases as well as higher levels of activated Smad2, Akt, Erk, p38, Rac1 and more vimentin in the tumor tissues in situ than tumors expressing Neu alone." (PMID 33478130, 2021).
tumor (continued). "We have previously demonstrated that tranilast, which is one of anti-allergic drugs, acted HPMCs resulted in inhibition of tumor growth and fibrosis by suppressing Smad2/3 phosphorylation of the TGF-β/Smad pathway." (PMID 32488650, 2021). "We have previously published that PANC-1 cells with SMAD2 knockdown have increased cell viability and tumor growth." (PMID 34439202, 2021). "Here, miR-494-3p was upregulated during tumor induction and growth; therefore its target, SMAD2, should be downregulated." (PMID 33947113, 2021). "Treated with TGF-β and SB to analyze the interrelationship of TGFβ and Smad2 and Smad3 on tumor proliferation and metastasis." (PMID 34712379, 2021). "We confirmed in vivo inhibition of canonical TGFβ signaling via the reduction in phosphorylated SMAD2/3 expressed in tumor-infiltrating CD45+ immune cells following isoform-specific and pan-TGFβ inhibition." (PMID 34789823, 2021). "Through mechanistically studies, we constructed a novel regulating axis of TRIM37/ub-H2A/TGF-β1/Smad2/3 signaling in regulating RCC tumor metastases and progression." (PMID 34130705, 2021). "On the one hand, HNK can inhibit the viability, mobility, and invasion of tumor cells via inhibiting the SMAD2/3 signaling." (PMID 34671554, 2021). "In the nucleus, SMAD2/3 acts as a tumor suppressor, restraining the increase of cell proliferation caused by PTEN deficiency." (PMID 34638474, 2021). "In conclusion, this study reveals that tumor-derived, exosome-mediated miR-125b possesses anti-metastatic properties by targeting SMAD2, as well as by inhibiting MMPs and TGF-β1/SMAD signaling pathway in EMT via intercellular communication." (PMID 34386414, 2021). "It is worth to note that while silencing of either Smad2 or Smad3 led to accelerated c-Myc tumor growth, silencing of Smad4 demonstrated the most significant tumor acceleration phenotype." (PMID 33608500, 2021). "This is an important pathway affecting cell proliferation, differentiation and apoptosis, with the inhibition of Smad2 being shown to promote tumor metastasis." (PMID 35087829, 2021). "Smad2 was found play a critical role in the basal epithelial or stem cell compartment of the prostate as a tumor suppressor." (PMID 34150649, 2021). "In the present report, we found that TGF-β treatment activated lnc-UTGF transcription via SMAD2/3, and lnc-UTGF in turn enhanced the TGF-β signaling by increasing the stability of SMAD2/4-mRNAs, which consequently promoted tumor metastasis." (PMID 34785655, 2021). "Surprisingly, sTβRIII activated Smad2 signaling in both models and decreased survival in LN-229 tumor-bearing mice." (PMID 33772427, 2021). "SMAD2 and SMAD3 mRNA levels are associated with nuclear and FIGO grades, and the SMAD4 mRNA level is significantly associated with tumor size, tumor subtype, lymphovascular invasion, nuclear and FIGO grade, and disease-free survival." (PMID 34501347, 2021). "A potential mechanism is that HAPLN1 regulates tumor cell proliferation via the TGF-β (Smad2/3, p-Smad2/3, and Smad4) signaling pathway." (PMID 34966673, 2021). "Mechanistically, CTBP1-AS2 regulated the malignant phenotype of tumor cells through the TGF-β/SMAD2/3 pathway." (PMID 33937030, 2021). "We also measured TGF-β1 and SMAD2/3 expression in tumor tissues by using immunohistochemistry or Western blotting." (PMID 33937030, 2021). "As the TGF-β cascade has a crucial role in tumor metastasis, we investigated the expression levels of its downstream effectors (i.e., SMAD2, SMAD4) in BCs using different public BC datasets." (PMID 33426510, 2021). "SMAD2 played its tumor promoter role by enhancing migration, invasion and proliferation abilities of HCC cells." (PMID 32746934, 2020). "Collectively, these results demonstrated that MIR22HG exerted its tumor suppressive function through competitively binding to SMAD2, thereby preventing the interaction between SMAD2 and SMAD4 in CRC cells." (PMID 32127004, 2020).
tumor (continued). "Depletion of PGC-like tumor cells through genetic depletion of any of key germ cell genes impairs liver metastasis, while increased PGC-like tumor cells by SMAD2 knockout is correlated with markedly enhanced liver metastasis." (PMID 32218989, 2020). "PC(36:5), (36:3), and (36:2) were increased in marginal tumour areas containing HNSCC cells with high p-SMAD2 levels." (PMID 32020064, 2020). "Nuclear SMAD2 expression was found in tumor cells of 45% of CRC samples and in tumor stroma of 70% of cases, in which CCBE1 expression was significantly lower than in the samples with cytoplasmic SMAD2 staining." (PMID 32089745, 2020). "In support, expression of SMAD2/3 target genes Cyr61 and Igfn1 is also reduced in the muscles of C26 tumor-bearing mice in response to TMEPAI expression." (PMID 33250771, 2020). "An online miRNA target prediction database (miRecords) showed that both Smad2 and Smad3, two well-known positive regulators of tumor metastasis, contained putative binding sites for miR-1258." (PMID 32372060, 2020). "Furtherly, UM-2 shOLA1 siR-SMAD2 cells were constructed to study the role of SMAD2 in OLA1 involvement in tumor migration." (PMID 32928102, 2020). "Expression of activated Smad2 promotes mesenchymal spindle tumor cell invasion, which also regulates the expression of Snail, Slug and Twist to suppress the expression of E-cadherin." (PMID 32517366, 2020). "In clinical human HNSCC tissues, this approach achieved determination of tumour areas with activated TGF-β signalling as efficiently as a conventional histopathological assessment using phosphorylated-SMAD2 staining." (PMID 32020064, 2020). "Collectively, the expression of tumor FOXP3 can inhibit the growth of HCC via suppressing c-Myc directly or indirectly via interacting with Smad2/3/4." (PMID 33116119, 2020). "We also examined the corresponding data between the predicted result obtained by machine learning and p-SMAD2 expression levels in each dissected tumour area." (PMID 32020064, 2020). "Especially, few downstream markers are used for evaluation of activated TGF-β signalling in tumour tissues instead of p-SMAD2 IHC." (PMID 32020064, 2020). "One study demonstrated that VEGF and TGFBR1 (ALK5) inhibitors can synergistically promote tumor angiogenesis by potentially blocking the downstream effectors of ALK5 such as Smad2 and Smad3." (PMID 32993787, 2020). "Mechanistically, MIR22HG exerts its tumor suppressive activity by competitively interacting with SMAD2 and modulating the activity of TGFβ pathway." (PMID 32127004, 2020). "Recently, miRNAs have been identified and shown to inhibit tumor growth and migration by regulating SMAD2." (PMID 33330073, 2020). "What is more, overexpression of miR-3613-3p substantially inhibited the migration and proliferation of TNBC cells in vitro and tumor proliferation in vivo by targeting SMAD2 and EZH2." (PMID 33330073, 2020). "To verify the tumor promoting function of SMAD2 in pan-cancer tissues, we analyzed the positive rates of SMAD2 in several cancer tissues." (PMID 33202380, 2020). "Next, mass spectra were obtained in positive-ion mode from the same tumour specimens in which p-SMAD2 expression was evaluated by IHC." (PMID 32020064, 2020). "The expressions of p-Smad2 and p-Smad3 in tumor tissues were notably decreased by LINC01234 knockdown." (PMID 33178601, 2020). "We also carried out the analysis of TMEPAI, Smad2 and Smad3 proteins in primary tumor tissues of TNBC." (PMID 31798766, 2019).